FOLH1 (folate hydrolase 1)
Diseases named in the same sentence as FOLH1 in open-access papers (continued):
Sharing a sentence is not in itself a finding about the gene and the disease.
prostate tumor (231 papers, 2006 to 2026). "We utilized a database of molecularly-profiled prostate tumors to evaluate clinical, genomic, and immunologic correlates of high FOLH1 RNA expression." (PMID 41056440, 2025). "This comprehensive molecular analysis of a large cohort of prostate tumors provides new insight into molecular correlates and oncologic outcomes of FOLH1." (PMID 41056440, 2025). "To address this need, we utilized a database of molecularly-profiled prostate tumors to evaluate correlates of high FOLH1 (PSMA) RNA expression." (PMID 41056440, 2025). "Lymph node metastases exhibited the highest FOLH1 expression levels, surpassing both primary prostate tumors and other metastatic sites." (PMID 41056440, 2025). "Several AR-associated genes (AR, FOLH1, KLK3, NKX3-1, TMPRSS2) showed minimal change in the metastatic dura adenocarcinoma as compared to the primary prostate tumor, while there was a marked downregulation of these AR-related transcripts in the metastatic brain NEPC lesion." (PMID 39349591, 2024).
lymph node metastases (168 papers, 2014 to 2026). "While lymph node metastases had significantly decreased expression compared to the kidney, FOLH1 expression in the bone, endocrine glands, skin, and gastrointestinal tract was numerically higher than that in the kidney." (PMID 38791934, 2024).
prostate adenocarcinoma (102 papers, 2011 to 2026). "Among the multiple types of cancers, FOLH1 (the gene encoding the PSMA protein) was highly expressed in prostate adenocarcinoma (PRAD), according to a pan-cancer analysis using the GEPIA website." (PMID 40469300, 2025). "Prostate adenocarcinoma had 2.97-fold higher FOLH1 expression compared to high-grade neuroendocrine prostate cancer (q < 0.0001)." (PMID 41056440, 2025). "PSMA is a transmembrane glycoprotein encoded by the folate hydrolase 1 gene (FOLH1) and is highly expressed in prostate adenocarcinoma." (PMID 36230766, 2022). "In descending order of importance for the prostate lineage genes, NKX3-1, KLK3, ACPP, SLC45A3 and FOLH1 were the most important predictors for prostate adenocarcinoma based on the discriminant loading > 0.3." (PMID 33762601, 2021). "For all subsequent molecular analyses, we stratified subgroups of prostate adenocarcinoma specimens (primary tumors, lymph node metastases, and other metastatic sites) into FOLH1-High and FOLH1-Low according to top (Q4) and bottom (Q1) quartiles of gene expression." (PMID 41056440, 2025). "Finally, we examined ARPI treatment-related OS in the entire prostate adenocarcinoma cohort, which also revealed improved OS for patients with high FOLH1 expression (HR = 0.779, P < .001)." (PMID 41056440, 2025). "Standard discriminant analysis of this study demonstrated that many of the prostate lineage markers genes were important predictors for prostate adenocarcinomas i.e. NKX3-1, KLK3, ACPP, SLC45A3 and FOLH1, corresponding to NKX3.1, PSA, PSAP, P501S, and PSMA respectively." (PMID 33762601, 2021). "We found that prostate adenocarcinoma had among the highest differences in expression of FOLH1 relative to its matched normal tissue, consistent with past investigations involving the use of PSMA-targeting theranostics and their successful implementation within the disease." (PMID 40227800, 2025). "Interestingly, canonical prostate adenocarcinoma cell-surface targets KLK2 and STEAP1 had significantly lower expression in the LumB versus LumA samples, and STEAP2 also had a trend toward lower expression in LumB, in contrast to FOLH1, which was highly expressed in both luminal CTC phenotypes." (PMID 39912912, 2025).
breast carcinoma (98 papers, 2006 to 2026). "Their analysis demonstrated that PSMA protein was predominantly expressed in basal-like breast cancer compared to other subtypes, which frequently exhibited FOLH1 amplification." (PMID 39941824, 2025). "By contrast, lung adenocarcinomas (LUAD), colorectal adenocarcinomas (COAD), and breast carcinomas (BRCA) overexpressed FOLH1 at a fold change of less than two, and these cancers have previously shown relatively low uptake and tumor-to-background ratios." (PMID 40227800, 2025).
glioblastoma (64 papers, 2014 to 2026). The most malignant astrocytic tumor (WHO grade IV). "To study PSMA (FOLH1) expression in the glioblastoma subtypes, we analysed 567 mRNA microarray samples using the TCGA GBM data set (and nomenclature from the TCGA)." (PMID 32390293, 2020).
glioma (59 papers, 2014 to 2025). A benign or malignant brain and spinal cord tumor that arises from glial cells (astrocytes, oligodendrocytes, ependymal cells). "The possibility that the expression of FOLH1 splice variants changes according to glioma grade and influences vascular expansion and tumor cell invasion should be investigated in follow-up studies." (PMID 24645697, 2014). "Grade 1 through IV gliomas which exhibit different behavior and gene signatures, may also have differential expression of FOLH1 splice variants." (PMID 24645697, 2014). "We also detected prominent expression of FOLH1, the gene encoding prostate specific membrane antigen (PSMA), in approximately 70% of the gliomas." (PMID 31747973, 2019).
melanoma (36 papers, 2011 to 2025). A malignant, usually aggressive tumor composed of atypical, neoplastic melanocytes. "FOLH1 is a transmembrane enzyme receptor that is upregulated on the cell membrane of PCa, intracellularly in melanoma cells and the neo‐vascular lumen of virtually all solid tumours (including PCa and melanoma)." (PMID 34541577, 2021).
ovarian carcinoma (28 papers, 2013 to 2025). A malignant neoplasm originating from the surface ovarian epithelium. "We first confirmed that gene expression of FOLR1 (for FRα) and of members of the folate signalling pathway (FOLH1, TYMS and DHFR), were elevated in ovarian cancer cell lines and ovarian cancer tissues, compared to normal tissues." (PMID 36402875, 2023).
colorectal cancer (26 papers, 2017 to 2025). A primary or metastatic malignant neoplasm that affects the colon or rectum. "However, FOLH1 and PSMA expression have been studied in ovarian, cervical, breast, and colorectal cancers." (PMID 38791934, 2024). "Although the differential patterns of FOLH1 and PSMA expression across tumor subtypes of ovarian, cervical, breast, and colorectal cancer have been evaluated, there remains a gap in the literature regarding the comparative analysis of FOLH1 RNA among subtypes of RCC." (PMID 38791934, 2024).
brain tumors (23 papers, 2014 to 2026). "When extending to all 15 pediatric brain tumor types (n ≥ 20), we observed that all pediatric brain tumors exhibit generally low FOLH1 expression levels, with a median log2 TPM of less than five." (PMID 40227800, 2025). "This study demonstrates that FOLH1 showed a lack of tumor-specific expression for both adult and pediatric CNS tumors when compared to normal brain tissue, suggesting that PSMA is not a desirable target in brain tumors." (PMID 40227800, 2025).
clear cell renal carcinoma (23 papers, 2018 to 2025). A malignant epithelial neoplasm of the kidney characterized by the presence of lipid-containing clear cells within a vascular network. "Kidney cancer subtypes varied considerably in terms of their FOLH1 expression relative to normal kidney tissue, with papillary and chromophobe carcinomas (KIRP and KICH, respectively) exhibiting underexpression and kidney clear cell carcinoma (KIRC) showing overexpression." (PMID 40227800, 2025).
renal carcinoma (18 papers, 2019 to 2025). A carcinoma arising from the epithelium of the renal parenchyma or the renal pelvis. "In this study, we applied this technology to determine that the expression of FOLH1, which encodes PSMA, is upregulated in tumor blood vessels surrounding renal cancer, and that the angiogenesis-related pathway is also upregulated in these areas." (PMID 39936957, 2025). "FOLH1, which encodes PSMA, was highly expressed in clusters of tumor blood vessels (Cluster 3) around renal cancer, but was hardly expressed in clusters of normal blood vessels (Cluster 6)." (PMID 39936957, 2025). "Spatial gene expression analysis revealed that FOLH1 expression, which codes PSMA, was upregulated in tumor blood vessels around renal cancer, and that angiogenesis-related pathways were enhanced." (PMID 39936957, 2025).
lymphoma (16 papers, 2020 to 2025). A malignant (clonal) proliferation of B- lymphocytes or T- lymphocytes which involves the lymph nodes, bone marrow and/or extranodal sites. "More recently, studies have explored the potential role of PSMA PET imaging in hematological malignancies, such as lymphoma and MM, primarily based on the expression of the FOLH1 gene, which encodes PSMA." (PMID 40227793, 2025).
schizophrenia (13 papers, 2013 to 2024). A major psychotic disorder characterized by abnormalities in the perception or expression of reality. "Conversely, GCPII levels are increased in the dlPFC of patients with schizophrenia, and gain-of-function mutations in FOLH1 that reduce NAAG-mGluR3 signaling are linked to inefficient cognition and lower scores on IQ tests in healthy subjects." (PMID 35732693, 2022). "GRM3 is a replicated GWAS risk gene for schizophrenia, and variations in FOLH1 genotype that increase GCPII expression and lower NAAG-mGluR3 signaling are associated with lower IQ scores." (PMID 34867287, 2021). "In contrast, the FOLH1 484 T allele load was positively associated with RBC folate levels in a sample of schizophrenia patients, and was associated with treatment response to L-methylfolate and vitamin B12 supplementation." (PMID 28885600, 2017). "Low folate levels have also been associated with the severity of negative symptoms in schizophrenia patients with specific variants in folate metabolism genes such as MTHFR or folate hydrolase 1 (FOLH1)." (PMID 36816414, 2023).
sarcoma (12 papers, 2017 to 2025). A usually aggressive malignant neoplasm of the soft tissue or bone. "In this review, mRNA expression of the FOLH1 gene which encodes PSMA, PSMA immunohistochemistry, PSMA-targeted imaging and PSMA-targeted therapy in sarcomas will be discussed." (PMID 36728839, 2023). "mRNA expression of the FOLH1 gene, immunohistochemical PSMA expression, PSMA-targeted imaging, PSMA-targeted therapy and the possible future perspectives for sarcomas will be discussed." (PMID 36728839, 2023).
neuroendocrine carcinoma (6 papers, 2006 to 2025). A malignant neuroendocrine neoplasm composed of cells containing secretory granules that stain positive for NSE and chromogranin. "We observed significantly lower FOLH1 expression in tumors exhibiting neuroendocrine differentiation compared to adenocarcinoma specimens, which was especially pronounced in pure high-grade neuroendocrine carcinoma." (PMID 41056440, 2025).
endometrial cancer (4 papers, 2013 to 2023). Primary or metastatic malignant neoplasm involving the endometrium (mucous membrane that lines the endometrial cavity). "We also found that rs202676, which is on the FOLH1 gene, was significantly associated with endometrial cancer incidence." (PMID 23299529, 2013).
gastric adenocarcinoma (4 papers, 2017 to 2025). "While stomach adenocarcinoma showed far higher FOLH1 expression than normal stomach tissue, expression was lower relative to kidney (log2FC = −0.71, p = 1.33 × 10−4), liver (log2FC = −2.38, p = 1.79 × 10−81), and salivary gland (log2FC = −2.47, p = 2.39 × 10−63)." (PMID 40227800, 2025).
oligodendroglioma (3 papers, 2022 to 2025). A well-differentiated (WHO grade II), diffusely infiltrating neuroglial tumor, typically located in the cerebral hemispheres. "Among pediatric CNS tumors, all illustrated lower expression of FOLH1 in at least two dose-limiting tissues with the exception of oligodendrogliomas, whose FOLH1 expression was either similar to or higher than that of the dose-limiting tissues of interest." (PMID 40227800, 2025).
vascular tumors (3 papers, 2006 to 2025). "While RCC is regarded as a vascular tumor, we hypothesized that less vascular metastatic sites would express lower FOLH1 and, conversely, more vascular sites would express higher levels." (PMID 38791934, 2024).
dementia (2 papers, 2017 to 2024). Loss of intellectual abilities interfering with an individual's social and occupational functions. "These speculations are consistent with our pathway analysis results which found that FOLH1 is enriched in disease-gene network analysis for memory impairment, amyloid plaque, memory loss, presenile dementia, and memory impairment." (PMID 38883718, 2024).
Merkel cell carcinoma (2 papers, 2021 to 2025). "Herein, FOLH1 expression in primary (p) and metastatic (m) Merkel cell carcinoma (MCC) is characterized to determine its targeting potential for J591‐brachytherapy." (PMID 34541577, 2021).
Obesity (2 papers, 2021 to 2022). Accumulation of substantial excess body fat. "In current study, the expression of BCL2L15 and FOLH1 in the mild to moderate obesity groups were shown in the significant changes compared to those in control group, whereas those genes were not belonged with the specific metabolic pathway in PBMC prepared form obese dogs." (PMID 34258471, 2021). "RT-PCR analysis showed downregulation of FOLH1, ALAS2 and LOC100855540 genes, and upregulation of BCL2L15 gene, suggesting that the metabolic difference between normal and mild to moderate obesity was involved in the hemoglobin metabolism." (PMID 34258471, 2021).
psychosis (2 papers, 2022). "A missense mutation in the FOLH1 gene that codes for GCPII (rs202676) was found to be associated with both increased GCPII expression and decreased brain NAAG levels in both patients with psychosis and unaffected healthy individuals." (PMID 34976589, 2022).
alveolar soft part sarcoma (1 paper, 2022). An alveolar soft part sarcoma occurring in adults. "In addition, inhibition of vascular endothelial growth factor receptor tyrosine kinases by cediranib has also been reported to regulate FOLH1 in Alveolar soft part sarcoma." (PMID 35162969, 2022).
folate deficiency (1 paper, 2017). A nutritional condition produced by a deficiency of FOLIC ACID in the diet. "Previous work suggests that the effect of certain polymorphisms on RBC folate status may be attenuated in high folate intake populations while upregulation of FOLH1 may be part of the physiological response to dietary folate deficiency." (PMID 28885600, 2017).
hyperhomocysteinemia (1 paper, 2014). A serious metabolic condition caused by mutations in the MTHFR gene, medications, or nutritional deficiency. "Furthermore, a polymorphism in FOLH1 associated with lower levels of serum folate and hyperhomocysteinemia has been described." (PMID 24252472, 2014).
neuralgia (1 paper, 2024). "The results revealed a notable mediation effect (βXY’ = 0.318, PXY’ = 0.001224558), so indicating that NAAG most certainly serves as a full mediator between FOLH1 and postherpetic neuralgia." (PMID 39650245, 2024). "UVMR estimate mediation effect of NAAG between FOLH1(CGPII) and postherpetic neuralgia." (PMID 39650245, 2024). "Furthermore, in the causal pathway NAAG most certainly serves as a complete mediator between FOLH1(CGPII) and postherpetic neuralgia." (PMID 39650245, 2024).
tumor (1,977 papers, 2004 to 2026). "FOLH1-High primary tumors were more frequently microsatellite instability-High, tumor mutational burden-High, and PD-L1-positive." (PMID 41056440, 2025). "Histone-deacetylase inhibitors and demethylating agents can re-induce FOLH1 expression in low-expression PSMA tumours, potentially making them susceptible to PSMA-targeted radioligands, but this remains validated only in vitro and requires further exploration." (PMID 41301079, 2025). "Recent studies further support this, showing that FOLH1 (PSMA-encoding gene) expression is associated with tumor angiogenesis and predicts progression-free survival in metastatic ccRCC (m-ccRCC) patients treated with VEGF inhibitors (VEGFi)." (PMID 39936957, 2025). "Second, our study revealed differential molecular and immune characteristics associated with FOLH1 expression within specific tumor sites, and an association of FOLH1 with AR signaling." (PMID 41056440, 2025). "Our genomic analysis revealed distinct patterns of alterations associated with FOLH1 expression levels across different tumor sites." (PMID 41056440, 2025). "The authors found PSMA decrease in tumor tissues caused by epigenetic changes of the FOLH1 gene, but treatment with a HDACi revoked this epigenetic downregulation and restored PSMA expression in vivo and in vitro." (PMID 37111295, 2023). "The first evidence of the association of NOS3 polymorphisms with circulating tumor cells was demonstrated between the intron 4 polymorphism and the folate hydrolase – prostate-specific membrane antigen (FOLH1) expression in the peripheral blood." (PMID 18823560, 2008). "We aimed to investigate the pan-tissue expression pattern of the PSMA-encoding gene FOLH1 to assess whether transcriptome profiling can inform tumor diagnostic and theranostic probes." (PMID 40227800, 2025). "Notably, TCGA-based analyses confirmed that expression of FOLH1 mRNA—which encodes PSMA—in tumor-associated blood vessels holds prognostic significance at the transcriptional level, supporting the potential use of PSMA-targeted imaging in RCC." (PMID 39936957, 2025). "Notably, CNS tumors universally exhibited lower expression of FOLH1 relative to normal brain tissue, but we observed considerable variation in the expression of blood–tumor barrier (BTB) components associated with reports of BTB integrity and uptake of PSMA radiotracers." (PMID 40227800, 2025). "We then comparatively evaluated the expression of FOLH1 across all tumor types relative to dose-limiting tissues based on the availability of data in the GTEx database, which included the kidney, liver, minor salivary gland, small intestine, and spleen." (PMID 40227800, 2025). "Investigating the tumor immune microenvironment by quanTIseq, significant differences (q < 0.05) were noted for most immune cell subsets between FOLH1-High and FOLH1-Low groups." (PMID 41056440, 2025). "Looping between enhancing and promoter regions, differential methylation, and histone-modification patterns can either activate or silence FOLH1 transcription, explaining why some high-grade tumours are PSMA-negative despite aggressive histology." (PMID 41301079, 2025). "Among our findings, the relationship between FOLH1 expression and tumor histology was particularly noteworthy." (PMID 41056440, 2025). "First, our results demonstrate low FOLH1 expression among tumors with neuroendocrine differentiation, as well as tumor site-specific differences in FOLH1 expression." (PMID 41056440, 2025). "Our analysis of the tumor immune microenvironment revealed a complex landscape in FOLH1-High tumors." (PMID 41056440, 2025). "At all tumor sites, the enrichment of M2 macrophages and depletion of M1 macrophages in FOLH1-High tumors was most striking, resulting in a lower M1:M2 ratio suggestive of immunosuppression (q < 0.0001)." (PMID 41056440, 2025).